RNU6-794P (RNA, U6 small nuclear 794, pseudogene)
Gene: Small nuclear RNA gene on chromosome 10 (35,231,331 to 35,231,394, reverse strand). Ensembl gene ENSG00000253070.
Homologues: Orthologues: chimpanzee U6 (98% identical), rat LOC120099417 (89% identical), dog U6 (86% identical), guinea pig U6 (84% identical), rabbit U6 (84% identical), dog U6 (83% identical), guinea pig U6 (81% identical), pig U6 (75% identical). Paralogues in human: RNU6-1243P (95% identical), RNU6-1024P (94% identical), RNU6-1029P (92% identical), RNU6-1060P (92% identical), RNU6-1122P (92% identical), RNU6-116P (92% identical), RNU6-1248P (92% identical), RNU6-24P (92% identical), RNU6-331P (92% identical), RNU6-48P (92% identical), RNU6-748P (92% identical), RNU6-829P (92% identical), and 1284 more.